TSLP (thymic stromal lymphopoietin)
Diseases named in the same sentence as TSLP in open-access papers (continued):
Sharing a sentence is not in itself a finding about the gene and the disease.
asthma (continued). "Some single nucleotide polymorphisms (SNPs) that are sex-specific and associated with asthma were discovered in beta 2 adrenergic receptors and thymic stromal lymphopoietin (TSLP)." (PMID 35769576, 2022). "The gene encoding thymic stromal lymphopoietin (TSLP) was implicated in asthma and allergic disease before the GWAS era, and an anti-TSLP antibody has been trialled in allergic asthma." (PMID 35104449, 2022). "TSLP is associated with the pathogenesis of type 2 inflammatory diseases, such as asthma, atopic dermatitis, and inflammatory bowel disease." (PMID 35321112, 2022). "TSLP has been implicated to play an important role in allergic diseases, such as asthma, atopic dermatitis, and inflammatory bowel disease." (PMID 35321112, 2022). "For example, asthma associates with damaged epithelial cells and activated myeloid cells, which produce alarmins such as IL-15, IL-25, thymic stromal lymphopoietin (TSLP), and IL-33, have been observed to directly activate ILC2s." (PMID 36466877, 2022). "The specific SNPs discovered in TSLP include rs1837253, associated with the risk of asthma in males, and r2289276 in females only." (PMID 35769576, 2022). "STAT3 upregulation and activation in the airways are closely associated with the onset and development of asthma, while STAT3 activation facilitates TSLP in asthma-associated airway remodeling." (PMID 36172292, 2022). "Air pollutants such as diesel exhaust particles can also amplify TSLP release triggered by allergens, which links decreasing air quality in heavily urbanised areas with an increased susceptibility of asthma and asthma exacerbation in urban centers." (PMID 36311787, 2022). "Recently, several studies showed that epithelium-derived cytokines, namely IL-25, IL-33, and TSLP, act as key regulatory factors in immune-pathogenic mechanisms of allergic rhinitis, asthma, and CRSwNP mainly involved in type 2 inflammatory responses." (PMID 35162939, 2022). "Cell based and animal model studies have implicated TSLP in allergic diseases, such as asthma, highlighting its key role in allergic type 2 responses in the airways and the TH2 polarization of the immune response to an allergic phenotype." (PMID 36245744, 2022). "TSLP has been linked to a variety of lesions, such as asthma, inflammatory arthritis, AD, and eczema." (PMID 36077570, 2022). "The expression of TSLP is increased in the airways of patients with asthma compared to in healthy individuals, and is correlated with disease severity and lung function; polymorphisms in TSLP are associated with asthma." (PMID 35432474, 2022). "At least in asthma, the role of TSLP is further underscored by genome-wide association studies that have found associations between asthma risk and single nucleotide polymorphisms (SNPs) in the TSLP gene." (PMID 35572064, 2022). "Neonatal RV infection resulted in induction of IL-33, IL-25, and TSLP–all of which are epithelial derived cytokines implicated in asthma pathogenesis–and in this model contributed to type 2 innate lymphoid cells (ILC2) expansion." (PMID 35493465, 2022). "Our study demonstrates for the first time that higher pulmonary TSLP levels obtained at baseline are linked to asthma disease severity in a subset of children." (PMID 36245744, 2022). "Genetic studies have shown that TSLP gene variants play a role in the development of asthma and are associated with the risk and severity of this disease, however, the results are inconsistent." (PMID 36292755, 2022). "In summary, our study demonstrates for the first time that lung TSLP levels at baseline are associated with asthma severity in the pediatric population." (PMID 36245744, 2022). "While the T allele of the TSLP SNP rs2289276 is significantly associated with a reduced risk of asthma in females, the T allele of rs1837253 is associated with a reduced risk of asthma in males." (PMID 35625578, 2022).
asthma (continued). "The epithelium-derived cytokines IL-33, TSLP, and IL-25 have been implicated in pathogenesis of asthma because they promote type 2 cytokine synthesis." (PMID 35524325, 2022). "After adjusting for age, gender, drinking, smoking, asthma and allergic status, hypermethylation at CpG3 and CpG22:23:24 of the thymic stromal lymphopoietin (TSLP) locus is still associated with CRSwNP." (PMID 36699454, 2022). "In eosinophils, the hallmark cell of asthma, TSLP, has been shown to prevent apoptosis; upregulate the adhesion molecule CD18; intercellular adhesion molecule-1; and induce IL-6, CXCL8, CXCL1, and CCL2, and downregulate expression of L-selectin." (PMID 35406669, 2022). "It binds thymic stromal lymphopoietin (TSLP), an epithelial-cell-derived cytokine implicated in the pathogenesis of asthma, preventing the interaction of TSLP with its receptor which is expressed on different immune cells of the type 2 inflammatory cascade." (PMID 34209312, 2021). "We investigated how homeostatic short TSLP (shTSLP) and asthma-associated long TSLP (loTSLP) regulate IgA production." (PMID 33808333, 2021). "Thymic stromal lymphopoietin (TSLP) is an innate cytokine, belonging to the group of alarmins, which plays a key pathogenic role in asthma by acting as an upstream activator of cellular and molecular pathways leading to type 2 (T2-high) airway inflammation." (PMID 33922072, 2021). "Airway TSLP is overexpressed in severe asthma, and it has been associated with steroid resistance of airway ILC2 in severe asthma." (PMID 35055325, 2021). "Thymic stromal lymphopoietin (TSLP) is a mucosal tissue-associated cytokine that stimulates a T-helper type 2 (Th2) response in allergic diseases such as asthma and atopic dermatitis, and therefore plays a key role in the pathogenesis of inflammatory diseases." (PMID 33536486, 2021). "In asthma pathogenesis, the overexpression of several type 2 inflammatory mediators including IgE, IL-4, IL-5, IL-13, and TSLP has been associated with ASM hyperreactivity, all of which can be targeted by humanized monoclonal antibodies (mAbs)." (PMID 34572466, 2021). "Activation of airway epithelium with allergens including Alt extract often causes severe asthma attacks and results in the release of several alarmins including IL-33, IL-25, GM-CSF, TSLP which orchestrate the downstream type 2 immune response." (PMID 34484177, 2021). "Thymic stromal lymphopoietin (TSLP) and variants near TSLP involved in Th2 inflammation induced by epithelial cell-derived cytokines also show significant associations with asthma." (PMID 34946955, 2021). "More recently, epithelial cytokines such as IL-33 and Thymic stromal lymphopoietin (TSLP) have been implicated the drive the development and/or exacerbation of asthma." (PMID 33808333, 2021). "We determined that previous history of severe-to-serious exacerbation, blood eosinophil counts, and serum tryptase and TSLP levels were independently associated with the risk of future exacerbation in severe asthma despite receiving multiple therapy." (PMID 33875671, 2021). "Ipetekimab is a monoclonal antibody targeting IL-33, another alarmin which associates with TSLP leading to an activation of T2-high inflammatory pathway in asthma." (PMID 34389053, 2021). "Genomic studies have shown that some single-nucleotide polymorphisms (SNPs) of the TSLP gene are associated with the risk of developing asthma." (PMID 33922072, 2021). "For the analysis of combined biomarkers predictive for the risk of asthma exacerbation, we first categorized the study subjects into 4 groups according to the serum TSLP levels and blood eosinophil counts." (PMID 33875671, 2021). "Given the association of IL-4, IL-5, IL-9, IL-13 and TSLP to asthma pathologies, all have been targeted with antibody-based therapeutics that bind either directly to the cytokines or their receptors." (PMID 34680614, 2021).
asthma (continued). "In regard to the crosstalk between innate and adaptive immunity underlying the cellular pathophysiology of asthma, TSLP exerts a pivotal function by acting at the level of dendritic cells." (PMID 33922072, 2021). "Thymic stromal lymphopoietin (TSLP) is a hallmark feature in allergic inflammatory diseases such as asthma and AR by potently deregulating Th2 responses as well as regulating epithelial barrier integrity." (PMID 33441633, 2021). "Their findings have suggested some biological plausibility for TSLP being a contributor and an indicator of asthma exacerbation, and highlight the potential pathogenic role of TSLP across different asthma phenotypes." (PMID 33875671, 2021). "TSLP has been found to be overexpressed in the airways of human patients with severe asthma, and has been linked to steroid-resistant asthma When blood ILC2 are exposed to TSLP, they become steroid resistant." (PMID 33418879, 2021). "Dysregulation of thymic stromal lymphopoietin (TSLP) expressions is linked to asthma and allergic disease." (PMID 33836808, 2021). "This leads us to suppose the existence of a link between periostin–TSLP and the Th2 response as asthma is mainly caused by Th2 inflammation with the predominance of mast cells and eosinophils in airways." (PMID 33203095, 2020). "Yet, emerging evidence suggests the involvement of the T2-promoting cytokines IL-25, IL-33, and TSLP in the response to respiratory viruses and associated exacerbations in asthma." (PMID 33255348, 2020). "TSLP has been implicated in asthma, with specific polymorphisms being associated with an increased susceptibility to developing the disease." (PMID 32714552, 2020). "TSLP is released in response to multiple triggers associated with asthma exacerbations, including allergens, viruses and other airborne particles." (PMID 33050934, 2020). "Sexual differences in asthma also result from gene polimorphisms including sex specific asthma risk loci and thymic stromal lymphopoietin (TLSP) and estrogen receptor alpha (ESR1) gene polimorphisms." (PMID 32102344, 2020). "TSLP is released in response to triggers associated with asthma exacerbations, such as allergens and viruses, and has been reported to be a potential mediator of corticosteroid resistance in patients with severe asthma." (PMID 33050928, 2020). "In a more recent study, the authors reported that TSLP gene promoter polymorphisms (rs3806933 and rs2289276) significantly increase susceptibility to asthma." (PMID 31210014, 2019). "At present, there is increasing evidence suggesting an association between TSLP elicited upon infection with hRSV or RV and the development of asthma." (PMID 31214165, 2019). "Previous genome‐wide association studies have documented an association between the TSLP SNPs and risk for allergy diseases, such as asthma and airway hyperresponsiveness." (PMID 31290290, 2019). "Another study showed that the rs1837253 SNP, which is located 5.7 kb upstream of the TSLP transcription start site, was linked to asthma in a Canadian population." (PMID 31290290, 2019). "Functionally TSLP is pleotropic; TSLP is described to have an important role in maintaining tolerance within the gut yet it is implicated in asthma and in the skin in both the development of itch and atopic inflammation." (PMID 31139177, 2019). "IL-33 (ILC2 activator, besides TSLP and IL-25)) was also associated to airway remodeling in steroid resistant asthma." (PMID 31395084, 2019). "Genetic variants located in or near TSLP have been detected in genome wide studies for asthma, rhinitis, and atopy." (PMID 30057581, 2018). "Genetic analysis has shown an association of polymorphisms in TSLP with several allergic diseases, including asthma and airway hyperresponsiveness, IgE concentrations, and eosinophilia." (PMID 30057581, 2018). "From 25 genome-wide association studies of asthma, 16 genes including TSLP were implicated in disease pathophysiology, as indicated by functional studies." (PMID 29670037, 2018).
asthma (continued). "The short isoform is constitutively expressed in several tissues and has been linked to TSLP homeostatic functions, while expression of the long isoform is inducible and appears to correlate with pathologies like asthma, AD or psoriasis." (PMID 29320511, 2018). "As a major finding of these projects, asthma onset has been associated with a number of genes coding for HLA, IL-13, IL-33, thymic stromal lymphopoietin [TSLP], IL-1 receptor-like 1 [IL-1RL1], ST2, and the receptor for IL-33." (PMID 29992143, 2018). "The existence of polymorphisms in the TSLP coding gene was also associated with the risk of developing AD or asthma." (PMID 30304837, 2018). "TSLP promotes Th2 cell responses associated with the pathogenesis of many inflammatory diseases, including atopic dermatitis and asthma, and is highly expressed by keratinocytes in AD lesions." (PMID 29862299, 2018). "Two candidate gene studies have suggested an interaction between active tobacco smoking and genetic variants in the occurrence of asthma in adults, i.e. the genes thymic stromal lymphopoietin (TSLP) and filaggrin (FLG)." (PMID 28253294, 2017). "Here we demonstrate that viral-induced HDM-asthma exacerbations associate with increased lung expression of three upstream cytokines whereas IL-33 and TSLP were also induced by HDM alone although to a lesser extent." (PMID 26879906, 2016). "Apart from predominant Th2 signature cytokines IL-13, IL-4 and IL-5, the critical role of IL-6, interferon (IFN)-γ, IL-25, IL-33 and thymic stromal lymphopoietin (TSLP) have been implicated in asthma." (PMID 27438823, 2016). "Among the candidate genes identified by GWAS, TSLP on chromosome 5 plays protective roles against the risk of asthma, atopic asthma and BHR across various ethnic groups." (PMID 27658857, 2016). "IL-25, IL-33 and TSLP have been associated with asthma in a number of investigations, both in the clinic and in animal models, and reduction in their levels should have an important influence on AHR and airway inflammation." (PMID 26214807, 2015). "Another potent cytokine which is released by inflamed epithelium and has been linked with asthma exacerbations is thymic stromal lymphopoietin (TSLP)." (PMID 26346739, 2015). "Lastly, we conducted a clinical study in asthmatic children to examine if rhinovirus-induced asthma exacerbations are in fact associated with in vivo airway secretion of TSLP and CCL11/eotaxin-1." (PMID 25546419, 2014). "Aberrant TSLP/TSLPR signaling has been associated with a variety of human diseases including asthma, atopic dermatitis, nasal polyposis, inflammatory bowel disease, eosinophilic eosophagitis and, most recently, acute lymphoblastic leukemia." (PMID 24573880, 2014). "TSLP has also been associated with the generation of airway eosinophilic responses during asthma exacerbations in human adult subjects." (PMID 25546419, 2014). "Recently, several independent genome-wide association studies have demonstrated that TSLP is a susceptibility locus for asthma." (PMID 24167583, 2013). "TSLP has been implicated in the development of asthma, atopic dermatitis, inflammatory arthritis, and other inflammatory disease conditions." (PMID 23738146, 2013). "Thymic stromal lymphopoietin (TSLP) is a key pro-allergic cytokine that has recently been linked to asthma." (PMID 24098299, 2013). "Genetic analyses of atopic populations have demonstrated polymorphisms in TSLP to be associated with asthma and airway hyperresponsiveness, IgE concentration, and eosinophilia." (PMID 22523502, 2012). "More recently, these authors demonstrated that TSLP polymorphisms were also associated with asthma in a sex-specific fashion." (PMID 22973903, 2012). "In contrast, a large study from Canada demonstrated that variant rs1837253, which is 5.7 kb upstream of the transcription start site of the TSLP gene, was associated with protection from asthma, atopic asthma, and airway hyperresponsiveness." (PMID 22973903, 2012).
asthma (continued). "In a more recent study these authors demonstrated that TSLP gene promoter polymorphisms (rs3806933 and rs2289276) were significantly associated with disease susceptibility in both childhood atopic and adult asthma." (PMID 22973903, 2012). "We found an inverse male-specific association between the T allele of SNP rs1837253 in TSLP and AR in three independent cohorts of children with asthma." (PMID 21244681, 2011). "Haplotype-specific score test indicated that an elevated risk for asthma was associated with a specific haplotype of TSLP involving SNP rs1898671 (OR = 1.58, 95% CI: 1.10–2.27, p = 0.01)." (PMID 21966427, 2011). "In summary, we found that the T allele of TSLP SNP rs1837253 was associated with reduced odds for AR in three independent cohorts of children with asthma." (PMID 21244681, 2011). "We found male-specific associations between TSLP SNP rs1837253 and AR in children with asthma from the Costa Rica, CAMP, and BAMSE studies." (PMID 21244681, 2011). "TSLP is an epithelial cell-derived cytokine in the IL-7 family that is mechanistically implicated with asthma in numerous human and animal models." (PMID 21966427, 2011). "We recently demonstrated sex-specific effects of TSLP polymorphisms on the regulation of specific, and total serum IgE in children with asthma." (PMID 21473777, 2011). "In a large Canadian population, a SNP (rs1837253) 5.7 kb upstream of the TSLP transcription start site was associated with asthma and the association was replicated in a large consortium study." (PMID 21966427, 2011). "Further support for a role for TSLP in the development of asthma comes from studies associating single nucleotide polymorphisms in the TSLP gene or its promoter region with an increased risk of developing asthma in childhood." (PMID 22574070, 2011). "We demonstrated that a SNP variant in TSLP is associated with clinical asthma in an urban population when adjusting for ancestry as well as additional covariates." (PMID 21966427, 2011). "We found that a SNP in TSLP was associated with reduced odds for AR in boys across the three cohorts of children with asthma." (PMID 21244681, 2011). "Across the three cohorts, the T allele of TSLP SNP rs1837253 was undertransmitted in boys with AR and asthma as compared to boys with asthma alone." (PMID 21244681, 2011). "In summary, we now suggest the association of a TSLP variant and asthma in an admixed population after adjusting for confounders and ancestry." (PMID 21966427, 2011). "In humans, TSLP has been linked to the pathogenesis of asthma, atopic dermatitis, and eosinophilic esophagitis." (PMID 21244681, 2011). "Ten tag-SNPs in the TSLP gene were analyzed for association with asthma using 387 clinically diagnosed asthmatic cases and 212 healthy controls from an urban admixed population." (PMID 21966427, 2011). "TSLP is a recently discovered, epidermally derived cytokine implicated in the pathogenesis of atopic dermatitis and asthma." (PMID 18507503, 2008). "A growing body of work has provided extensive evidence that TSLP overexpression in skin or lung epithelia can cause local allergic inflammation and subsequent development of atopic dermatitis and asthma, respectively." (PMID 18507503, 2008). "Additionally, a multi-center prospective study found that serum TSLP and tryptase levels, combined with blood eosinophil counts, help predict asthma exacerbation risk in severe asthma patients." (PMID 40503233, 2025). "The pivotal pathogenic role played by TSLP in asthma is due to its capability of acting as an upstream driver of multiple cellular and molecular proinflammatory pathways, responsible for the development and persistence of both type 2 (T2-high) and T2-low asthma." (PMID 41321706, 2025). "Furthermore, patients with values of TSLP > 5.74 cells/mm2 had a 2-fold higher probability of being a severe MIXED asthma (AUC 0.77; diagnostic OR = 2.0); sensitivity was 75.0% and specificity 62.5%." (PMID 40022191, 2025).